LGALS3 (galectin 3)
Diseases named in the same sentence as LGALS3 in open-access papers (continued):
Sharing a sentence is not in itself a finding about the gene and the disease.
breast carcinoma (continued). "The role of M2 TAMs in promoting proliferation, invasion, migration and angiogenesis in human breast cancer seems to be related to the NF-κB-mediated expression and secretion of galectin-3, a member of the β-galactoside binding proteins." (PMID 38397187, 2024). "Of note, it has been proposed that the angiogenic activity of galectin-3, at least in breast cancer, is dependent on proteolytic cleavage of the galectin-3 N-terminal tail." (PMID 38990363, 2024). "Studies in breast cancer have demonstrated that cells overexpressing galectin-3 exhibit increased migration, whereas downregulation of galectin-3 expression is associated with reduced tumor growth and diminished migratory capacity." (PMID 39451592, 2024). "NT-proBNP, ST2, and galectin-3 correlate with reduced LVEF among breast cancer patients receiving anthracycline therapy." (PMID 38138937, 2023). "Recently, elevations in galectin-3 were correlated with the development of anthracycline-induced cardiac toxicity in breast cancer patients, but there are limited data on the role of galectin-3 in the breast cancer population." (PMID 38138937, 2023). "In the current study, we explored the possibility of employing BDNF, NT-3 and galectin-3 as biomarkers to identify lesions of the peripheral nervous system in women following breast cancer treatment." (PMID 37092524, 2023). "The concentrations of soluble CD163, a marker of macrophages M2 and galectin 3 (Gal3), rather related to M1 macrophages, in the plasma of healthy controls and breast cancer patients were also determined." (PMID 33916440, 2021). "Cancer cell-derived factors, Wnt7a via TGF-β-dependent signaling in breast cancer and galectin-3 via integrin beta 1/ILK/NF-κB signaling in pancreatic cancer, have been reported to be involved in the malignant transformation of fibroblasts and stellate cells." (PMID 34885065, 2021). "Selected compounds are then tested with galectin-3 positive MCF 7 breast cancer cells using an in vitro would scratch assay." (PMID 32715650, 2020). "In the MCF-7 breast cancer line, nAChR activation by nicotine led to a decrease in staurosporin-induced cell death, which was associated with activation of the α9 nAChR/STAT3/Galectin-3 pathway." (PMID 32272633, 2020). "An in vitro wound scratch assay using a galectin-3 positive MCF 7 breast-cancer cell line further revealed that structures containing sulfonated and sulfated nonglycosidic motifs delayed wound closing by almost 20%." (PMID 32715650, 2020). "We observed that oleocanthal treated MCF7 breast cancer cells showed robust galectin-3 translocation to lysosomes, similar to that observed with the established LMP inducer LLOMe." (PMID 31412041, 2019). "Galectin-3 downregulation during breast cancer progression regulated tumor and microenvironmental GAGs and contributed to the metastatic phenotype." (PMID 31949431, 2019). "Galectin-3 is connected to several tumor properties, including chemoresistance and stem cell properties in breast cancer." (PMID 31191614, 2019). "We then evaluated the relevance of tumor and microenvironmental Gal-3 to breast cancer biology and performed an orthotopic injection of 4T1-scramble (SC) or 4T1-shRNA-Gal-3 (SH) cells in Lgals3+/+ (WT) or Lgals3−/− Balb/c female mice." (PMID 31949431, 2019). "The genetic manipulation of galectin-3 expression levels in tumor cells showed that downregulation of galectin-3 lead to tumor growth inhibition, whereas the upregulation of galectin-3 led to enhanced tumor growth in human cervical and breast cancer models." (PMID 31134055, 2019). "Galectin-3, in fact, is expressed in different primary and metastatic tumors (i.e., melanoma, breast carcinoma, prostatic carcinoma)." (PMID 29393868, 2018). "Conversely, in a different set of experiments, which used a thyroid cancer and a breast carcinoma cell line, inhibition of galectin-3 expression by using mRNA interference reverted the transformed phenotype." (PMID 29393868, 2018).
breast carcinoma (continued). "Galectin-3 is over expressed in Breast cancer cells, and antagonize the cytotoxic effects of different drugs such as staurosporine, and cisplatin as well as stimuli like radiation, and nitric oxide by inhibiting the intrinsic apoptotic pathway." (PMID 30224635, 2018). "Serum free media decreases galectin-3 secretion, while the serum protein fetuin can stimulate rapid export of galectin-3 from breast cancer cells." (PMID 29501720, 2018). "Galectin-3 (Gal-3) was proven to have oncogenic and angiogenic properties, being up-regulated, for example, in metastatic melanoma and breast cancer cells." (PMID 28320399, 2017). "Boscher and Nabi observed that EGF promoted MDA-MB-231 breast cancer cell migration in a phosphocaveolin-1 and galectin-3-dependent manner, enabling the metastatic spread of these cells." (PMID 27242966, 2016). "For example, stressing conditions, such as hypoxia and nutrient deprivation, induce galectin-3 expression in breast cancer and glioblastoma." (PMID 27242966, 2016). "In our study, we used an orthotopic 4T1 breast cancer model established in Lgals3−/− mice as a suitable experimental animal model to study the role of host galectin-3 in primary tumor growth and metastatic spread." (PMID 27526676, 2016). "In our study, balb/c Lgals3+/+ and Lgals3−/− female mice were inoculated in the fourth mammary fat pad with 4T1 breast cancer cell line." (PMID 27526676, 2016). "At the tissue level, galectin-3 accumulates in hypoxic/nutrient-deprived areas from both glioblastoma and mammary tumors." (PMID 27242966, 2016). "Over-expression of galectin-3 into human T lymphoma Jurkat cells results in faster growth in vitro, while inhibition of galectin-3 expression attenuates the growth of breast carcinoma and thyroid papillary carcinoma cells." (PMID 25889839, 2015). "Previously, our group had described increased galectin-3 expression in viable cells of mammary carcinomas surrounding necrotic areas." (PMID 26222311, 2015). "Galectin-3 was shown to be down-regulated in primary canine mammary carcinomas when compared to adenomas suggesting a possible selective advantage for malignant growth when the level of this lectin is decreased." (PMID 26222311, 2015). "A recent report showed that galectin-3 is involved in the nicotine-induced promotion of apoptosis resistance of breast cancer cells and that it promotes cancer cell growth and protects cells from apoptosis induced by chemotherapeutic drugs." (PMID 26273429, 2015). "We performed 123I-mIBG scintigraphy, conventional and strain echocardiography and biomarker (NT-proBNP, TNF-α, galectin-3, IL-6, troponin I, ST-2 and sFlt-1) assessment in 59 breast cancer survivors 1 year after anthracycline treatment." (PMID 26400150, 2015). "Given that catalase induces apoptosis in MCF7 breast cancer cells and that galectin-3 has an anti apoptotic role it is possible that that the up-regulation of galectin-3 is a cell survival mechanism against the catalase-induced apoptosis." (PMID 26222311, 2015). "In order to demonstrate the putative role of hypoxia in regulating galectin-3 expression in canine mammary tumors (CMT), in vitro and in vivo studies were performed." (PMID 26222311, 2015). "In order to assess a possible regulation of galectin-3 by hypoxia in neoplastic settings, we used a highly metastatic canine mammary cancer cell line, CMT-U27." (PMID 26222311, 2015). "High expression of galectin-3 was also observed in breast cancer patients, both on tumor cells and tumor–stromal cells of most specimens." (PMID 24982845, 2014). "We also evaluated the role of galectin-3 in the ATO-induced apoptosis of breast cancer cell lines using shRNA-mediated knockdown." (PMID 25254965, 2014). "Immunohistochemical examination revealed that galectin-3 was located in the cytoplasm and membrane of breast cancer cells, and was expressed significantly more strongly in breast tumors compared to paracancerous tissue." (PMID 25254965, 2014).
breast carcinoma (continued). "Galectin-3 expression was shown to increase migration and/or invasion of many tumor types, such as breast cancer, melanoma, lung cancer, sarcoma, gastric cancer, and chronic myelogenous leukemia (CML) in vitro." (PMID 24982845, 2014). "Apoptosis was only weakly induced by arsenic trioxide (ATO) treatment in galectin-3-positive breast cancer cells (MDA-MB-231 and MCF-7), although ATO treatment up-regulated galectin-3 expression." (PMID 25254965, 2014). "Correlations between Galectin-3 expression and chemotherapeutic resistance in breast cancers (n = 135)." (PMID 25254965, 2014). "Galectin-3 was expressed in both breast cancer cell lines, but was significantly upregulated in MDA-MB-231 cells after ATO treatment." (PMID 25254965, 2014). "Overall, triple-negative breast cancers expressed galectin-3 more strongly than did other breast cancers types (63.59% vs 21.36%, P = 0.001)." (PMID 25254965, 2014). "One study investigating alterations in galectin-3 expression and distribution within tumour cells in a mouse xenograft model has demonstrated that upregulated galectin-3 is correlated with breast cancer progression." (PMID 23285151, 2012). "Galectin-3 expressed on the endothelial cell surface has been shown to promote adhesion of breast cancer cells to the endothelium by interaction with cancer- associated Thomsen-Friedenreich antigen cell surface molecules." (PMID 23265237, 2012). "Further investigations into one of these proteins, galectin-3, demonstrates that targeting a marker enriched on breast cancer stem cells affects self-renewal of cancer stem cells and tumourigenicity in vivo." (PMID 23285151, 2012). "In relation to breast cancer, galectin-3 has a described role in enhancing metastatic disease through resistance to the products of inducible nitric oxide synthase and through its bcl-2-like anti-apoptotic properties." (PMID 23285151, 2012). "Galectin-3 has effects on K-ras signaling in breast cancer cells and its nuclear translocation increases resistance to chemotherapy." (PMID 22039439, 2011). "We also demonstrated that the metastatic genes OPN and Galectin-3 are Runx2-targets in metastatic breast cancer cells." (PMID 20591170, 2010). "The role of galectin-3 in breast cancer progression was also demonstrated by using three-dimensional co-culture system that recapitulates in vivo reciprocal functional breast epithelial-endothelial cell-cell and cell-matrix interactions." (PMID 23658855, 2010). "Several early studies indicated a reduced expression of galectin-3 in advanced histological grades of breast cancer." (PMID 23658855, 2010). "As the cleaved protein increases during cancer progression, the levels of intact protein decrease and thus explain the discrepancy in the previous data emphasizing the usefulness of galectin-3 as a breast cancer biomarker." (PMID 23658855, 2010). "Preliminary experiments with different galectin-3 positive tumors including melanomas, lymphoma and breast carcinomas were also considered for this purpose with overlapping results (data not shown)." (PMID 19020658, 2008). "In most of the studies on breast cancer and galectins, galectin-3 expression played a protective role in cell survival through various pathways, including the response to DNA damage and repair, as well as the inhibition of apoptosis following chemotherapy treatment." (PMID 39337581, 2024). "Blood levels of Galectin-3 are often increased during inflammatory conditions, however, high Galectin-3 blood levels have also been detected in several cancers including colon, head and neck, liver, gastric, endometrial, thyroid, skin, bladder and breast carcinomas." (PMID 39759523, 2024). "In addition, increased galectin-3 expression is involved in the liver metastasis of colorectal cancer and promotes breast cancer metastasis." (PMID 37433225, 2023).
breast carcinoma (continued). "Interestingly, the other upregulated genes are associated with features of cell proliferation (TNFRSF12A in human hepatocellular carcinoma), tumor progression (ISG20 in clear cell renal cell carcinoma), and cell survival (LGALS3 in breast cancer)." (PMID 37685859, 2023). "Previous studies suggested that galectin-3 activates Wnt signaling in human breast cancers." (PMID 37185758, 2023). "Elevation in galectin-3 was recently correlated with the development of anthracycline-induced cardiotoxicity in breast cancer patients, but there remains limited data on the role of galectin-3 in the breast cancer population." (PMID 38138937, 2023). "Using JIMT-1 breast cancer cells, the authors reported striking differences in the cellular uptake of the inhibitors and their ability to reduce the accumulation of galectin-3 around chemically-induced disruption of intracellular vesicles of JIMT-1 breast cancer cells." (PMID 37753083, 2023). "However, the effect of galectin-3 on malignant properties of cells is different in each tumor, and galectin-3 promotes adhesion to laminin in several breast cancer cell lines." (PMID 35204696, 2022). "LGALS3 (galectin 3), a member of the galectin family of carbohydrate-binding proteins, has previously been reported to induce apoptosis in human breast cancer cell lines through TRAIL signals that were dependent on increased PTEN activation and decreased PI3K/AKT survival pathway." (PMID 36529823, 2022). "The anti-apoptotic role of galectin-3 in breast cancer contributes to resistance to chemotherapeutic agents and might have an effect during the development of acquired resistance in melanoma." (PMID 34885166, 2021). "More importantly, LGALS3 could increase the metastatic potential of breast cancer, might accounting for the metastatic potential of HCC." (PMID 32849813, 2020). "Galectin-3, a β-galactoside–binding protein that is upregulated in multiple types of cancers including breast, was found to promote β-catenin/Wnt signaling in tongue squamous cell carcinoma and breast cancer cells." (PMID 32373510, 2020). "Moreover, during the metastatic process, inside blood vessels, breast cancer cells have been reported to reexpress cytoplasmic Galectin-3, contributing to their attachment to blood vessels." (PMID 31949431, 2019). "Moreover, galectin-3 induced migration and invasion of mammary carcinoma cells involved integrin clustering and ligand induced integrin activation." (PMID 30765738, 2019). "Likewise, in the reconstitution of galectin-3 in the TRAIL-resistant breast cancer cell line BT459, expressing low levels of the lectin was found to restore apoptosis induced by TRAIL through a mechanism associated with a decrease in AKT phosphorylation." (PMID 29498673, 2018). "Galectin-3 is necessary for optimal activation of K-Ras/MEK pathway in breast cancer cells." (PMID 27242966, 2016). "Recently, Shetty and colleagues observed that galectin-3 promotes cell migration through its association with annexin A2 (AnxA2) on the plasma membrane of HER-2 negative breast cancer cells." (PMID 27242966, 2016). "Interestingly, an interaction between another galectin, galectin-3, and N-cadherin has recently been described in a mouse mammary tumor cell line and this interaction can also modulate the dynamics of cell junctions." (PMID 25741714, 2015). "Recently, we and Chammas’s group showed galectin-3 overexpression around necrotic areas of canine mammary tumors (CMT) and breast ductal carcinoma in situ, respectively and suggested a link between hypoxia and the expression of different glycoconjugates in vivo." (PMID 26222311, 2015). "Based on these results, we propose a model to reconcile the overexpression of galectin-3 in necrosis surrounding areas of canine mammary cancer lesions and suggest that this might be a critical player in metastasis." (PMID 26222311, 2015).
breast carcinoma (continued). "Galectin-3 might be a subtype-specific marker for breast cancer, and a potential target in overcoming resistance to chemotherapy." (PMID 25254965, 2014). "Galectin-3 is known to have an anti-apoptotic role, and its high expression level in breast cancer cells might contribute to the inhibition of ATO-induced apoptosis." (PMID 25254965, 2014). "We further studied the relationships between patient age, tumor size, histological grade, histological type, molecular type, cancer stem cell (CSC) ratio, galectin-3 expression, and chemotherapeutic sensitivity in 135 breast cancer cases involving neoadjuvant chemotherapy." (PMID 25254965, 2014). "Therefore, we examined 1086 mastectomy specimens obtained from breast cancer patients in order to investigate the expression of galectin-3 in relation to clinicopathological features, survival, and chemotherapeutic resistance." (PMID 25254965, 2014). "Our results suggest that galectin-3 and Galß1,3-GalNAC glycosylated glycoproteins represent important elements in fibroadenomas’ development, reinforcing the notion that lectins constitute a very useful tool for the study of breast cancer." (PMID 23265237, 2012). "Galectin-3 promotes metastasis in experimental breast cancer metastasis models." (PMID 22039439, 2011). "Preliminary data of in vivo imaging of galectin-3 positive melanomas, lymphomas and breast carcinomas have been also obtained opening interesting possibilities for the future to use radio labeled mAbs to galectin-3 for in vivo imaging and treatment of different types of human malignancies." (PMID 19020658, 2008). "In addition, LGALS3 is highly expressed and implicated in different cancer types progression such as HCC, gastric, colorectal, pancreatic carcinomas, melanomas or glioblastomas and breast cancer." (PMID 38643145, 2024). "Similarly, there were no significant changes in the cardiac transcript levels of the inflammatory markers interleukin 1β, interleukin 18, monocyte chemoattractant protein-1, Galectin-3 (Mac-2), or the number of Galectin-3 (Mac-2)–positive cells in all groups of our mouse model of breast cancer." (PMID 37969640, 2023). "This indicates that galectin-3 might be a new biomarker enriching CSCs in breast cancer." (PMID 35788566, 2022). "The JIMT-1 breast cancer cell line was chosen for the remaining experiments due its growth pattern (i.e. the cells do not grow tightly together in patches or on top of each other) and due to the relatively flat morphology of the cells, making galectin-3 puncta easier to quantify." (PMID 30778105, 2019). "Moreover, overexpression of galectin-3 has been reported in multiple types of human tumors, including: ovarian cancer; pancreatic cancer; breast cancer; thyroid, gastric and colon cancer; hepatocellular, head and neck, prostate cancer, and glioma; T lymphoma, Burkitt lymphoma, and cervical cancer." (PMID 30585294, 2019). "However, the clinical and prognostic implications of galectin-3 expression in breast cancer remain unclear." (PMID 25254965, 2014). "However, the clinical and prognostic significance of galectin-3 expression in breast cancer remain unclear." (PMID 25254965, 2014). "LGALS3 total protein expression was found to be higher in clear cell RCC primary tissues, GBM, and LIHC, and lesser in the breast cancer, colon cancer, LUAD, HNSC, LUSC as well as UCEC primary tissues than in normal tissues." (PMID 38643145, 2024). "Galectin-3 (LGALS3, also called GAL3) is commonly overexpressed by cancer cells and promotes cancer progression and metastasis for several cancers, such as PCa, breast cancer, and colon cancer." (PMID 36980585, 2023). "The authors reported that one of their inhibitors blocked amitriptyline-induced vesicle damage in breast carcinoma MCF-7 cells, possibly by blocking the interaction between galectin-3 and LAMP1/2 proteins." (PMID 37753083, 2023).